NSD2 (nuclear receptor binding SET domain protein 2)
Diseases named in the same sentence as NSD2 in open-access papers (continued):
Sharing a sentence is not in itself a finding about the gene and the disease.
prostate carcinoma (37 papers, 2014 to 2025). A carcinoma that arises from epithelial cells of the prostate gland. "In sum, this study also supported the role of NSD2 in causing an immunosuppressive tumor microenvironment in prostate cancer." (PMID 40586874, 2025). "In prostate cancer, high NSD2 expression is associated with immunosuppressive phenotype, whereas NSD2 inhibition increases tumor-infiltrating CD8+ T cells." (PMID 41301842, 2025). "Another study also identified that NSD2 is a critical cancer driver facilitating metastasis of prostate cancer." (PMID 41301842, 2025). "An example of this includes a study performed in prostate cancer in which NSD2 overexpression was correlated with reduced immune infiltration and suppression of anti-tumor immunity." (PMID 40586874, 2025). "In castration-resistant prostate cancer cells, NSD2-mediated H3K36me2 upregulates the expression of vascular endothelial growth factor-A (VEGF-A), a key regulator of angiogenesis." (PMID 41301842, 2025). "Studies have also shown overexpression of NSD2 in multifarious solid tumors, including lung cancer, prostate cancer, colorectal cancer, cervical cancer, breast cancer, and osteosarcoma." (PMID 38400589, 2025). "Collectively both these studies identified NSD2 as a target for enhancing anti-tumor immune response against prostate cancer and as a potential therapeutic candidate for combination with immune checkpoint inhibitors and other immunotherapeutic agents." (PMID 40586874, 2025). "For example, NSD2 plays an important role in promoting the metastatic behavior of prostate cancers, which is consistent with the fact that H3K36me2 modification is generally associated with EMT and cancer cell metastasis." (PMID 40097917, 2025). "Concordantly, a dual NSD1/2 PROTAC degrader, called LLC0150, was preferentially cytotoxic in AR-dependent prostate cancer as well as NSD2-altered hematologic malignancies." (PMID 38464251, 2024). "NSD2 expression is abnormally gained in prostate cancer cells and its functional inhibition impairs AR trans-activation potential through partial off-loading from over 40,000 genomic sites, which is greater than 65% of the AR tumor cistrome." (PMID 38464251, 2024). "Altogether, we identify NSD2 as a novel subunit of the AR neo-enhanceosome that wires prostate cancer gene expression programs, positioning NSD1/2 as viable paralog co-targets in advanced prostate cancer." (PMID 38464251, 2024). "NSD2 expression is abnormally induced in prostate cancer, where its inactivation impairs AR transactivation potential by disrupting over 65% of its cistrome." (PMID 39251788, 2024). "NSD2 overexpression was observed in prostate cancer tissues compared with corresponding normal tissue samples." (PMID 38062230, 2023). "Previous studies have shown that NSD2 inhibition potently enhances antigen processing and presentation via complex epigenetic remodeling of prostate cancer cells and that the IFN-γ signaling pathway increases MHC expression to stimulate antitumor immunity." (PMID 38062230, 2023). "The upregulation of NSD2 expression acts as a key function for prostate cancer cell proliferation, survival, and tumor angiogenesis, and ATAD2 acts as an AR co-activator that enhances its transcriptional activity." (PMID 36008934, 2022). "NSD2 overexpression is detected in close to 80% of prostate cancer, which is correlated with prostate-specific antigen (PSA) progression and poor OS." (PMID 34671018, 2021). "NSD2 silencing by specific short hairpin RNA (shRNA) inhibited prostate cancer cell growth, proliferation, and migration in vitro, and abrogated prostate cancer metastasis in vivo." (PMID 34671018, 2021). "NSD2 is also a putative cofactor of androgen receptor, important for advanced prostate cancer progression." (PMID 34671018, 2021).
prostate carcinoma (continued). "Accumulating evidences have indicated that NSD2 also functions as an oncogene in several solid tumors, such as lung, colorectal, renal, cervical, prostate cancer, hepatocellular carcinoma, and osteosarcoma." (PMID 33665162, 2020). "Clinicopathologic associations of NSD2, known to di- and tri-methylate H3K36 (H3K36me2, H3K36me3), have been reported in endometrial cancer, prostate cancer, and SCCHN." (PMID 33050946, 2020). "In prostate cancer, increased NSD2 led to the transformation of indolent prostate tumors to metastatic cancer." (PMID 31692936, 2019). "Among the various metastasis-related genes, the highest level of metastasis-related activity was observed for the histone methyltransferase, Nuclear Receptor Binding SET Domain Protein 2 (NSD2), robustly expressed in lethal prostate cancer." (PMID 31366128, 2019). "In prostate cancer, metformin cooperates with NSD2 (previously termed MMSET) to reduce migration and invasion." (PMID 30453544, 2018). "Here they do cross-species computational analysis and identify nuclear receptor binding SET domain Protein 2 (NSD2) as a driver of prostate cancer metastasis." (PMID 30518758, 2018). "In particular, nuclear receptor binding SET Domain Protein 2 (NSD2) is robustly expressed in lethal prostate cancer in humans, while its silencing inhibits metastasis of mouse allografts in vivo." (PMID 30518758, 2018). "In particular, we have identified NSD2 as a conserved master regulator of metastatic prostate cancer progression and a robust marker of lethal prostate tumors." (PMID 30518758, 2018). "In the past years, NSD2 has been shown to be overexpressed in a variety of solid tumors including prostate cancer, where it has been found overexpressed in metastatic PCa compared to primary tumors and is associated with biochemical recurrence [1••]." (PMID 29888169, 2018). "To further evaluate the relationship of NSD2 expression with progression to lethal prostate cancer, we examined matched sets of primary tumors and metastases from the same patient (n = 3)." (PMID 30518758, 2018). "In human prostate cancer, we found that NSD2 expression is increased during cancer progression at both the mRNA and protein levels." (PMID 30518758, 2018). "A recent study also demonstrated that NSD2 plays a pivotal role in prostate tumorigenesis, where NSD2-mediated H3K36me2 is required for androgen receptor (AR) transactivation through de novo formation of tumor-specific AR enhancers in AR-dependent prostate cancer." (PMID 41301842, 2025). "Further investigation into the role of NSD2 in prostate cancer is warranted." (PMID 33050946, 2020). "High NSD2 protein expression determined by immunohistochemistry has been reported as an independent predictor of biochemical recurrence in a cohort of 108 patients with prostate cancer following radical prostatectomy." (PMID 33050946, 2020). "Interestingly, transcriptional targets of NSD2 in prostate cancer cells are highly enriched for components of the NF-kB-network, including IL-6, IL-8, survivin/Birc5, and VEGFA." (PMID 29888169, 2018). "Nonetheless, our study demonstrates that NSD2 is a functional driver of prostate cancer metastasis and suggests that it may be target for treatment of advanced prostate cancer." (PMID 30518758, 2018). "Further In vitro studies strengthened the role of NSD2 in prostate cancer tumorigenesis; it has been shown that NSD2 modulates Twist family bHLH transcription factor 1 (TWIST1) to promote epithelial to mesenchymal transition and invasiveness in prostate cancer cell lines." (PMID 29888169, 2018). "In particular, we have demonstrated that the Nuclear receptor binding SET Domain Protein 2 (NSD2) is a robust marker of lethal metastatic prostate cancer and a key driver of prostate cancer metastasis, extending previous studies that have reported the relevance of NSD2 in prostate cancer." (PMID 30518758, 2018).
prostate carcinoma (continued). "Similarly, another study that also found increased NSD2 expression with prostate cancer progression demonstrated that high NSD2 expression was positively correlated with the infiltration level of CD4+tumor-infiltrating lymphocytes (TILs) and negatively correlated with that of CD8+TILs." (PMID 40586874, 2025). "A previous study has shown that EZH2 may function upstream of NSD2 in prostate cancer." (PMID 33665162, 2020). "In prostate cancer, AKT signaling stabilizes NSD2 protein to enhance its H3K36me2 activity and subsequent transcriptional programs that support invasive behavior." (PMID 41301842, 2025). "It has been reported that upregulation of NSD2 is correlated with increased expression of IL‐6 and TNF‐α via NF‐κB in prostate cancer." (PMID 38400589, 2025). "NSD2 contributes to AR cistrome reprogramming during prostate cancer progression, and its degradation via a novel PROTAC reduces prostate cancer cell viability in vitro." (PMID 39251788, 2024). "Altogether, we characterize NSD2 as an essential AR neo-enhanceosome subunit that enables its oncogenic activity, and position NSD1/2 as viable co-targets in advanced prostate cancer." (PMID 39251788, 2024). "NSD2 inactivation also engenders increased dependency on the NSD1 paralog, and a dual NSD1/2 PROTAC degrader is preferentially cytotoxic in AR-dependent prostate cancer models." (PMID 39251788, 2024). "In prostate cancer cells, Asangani found that EZH2 catalyzes H3K27 trimethylation to inhibit miR-26a, miR-31, and miR-203, which target the 3’-UTR of NSD2." (PMID 33665162, 2020). "To evaluate the functional consequences of NSD2 for disease progression and metastasis, we used the mouse NPK metastatic allograft model as well as human DU145 prostate cancer cells, which model aggressive disease." (PMID 30518758, 2018). "A study suggests a novel role for NSD2 in the immune infiltration of prostate cancer, with elevated levels of the WHSC1 enzyme limiting lymphocyte infiltration in prostate cancer tumours, and positively correlating with the presence of an immunosuppressive microenvironment." (PMID 38062230, 2023). "Together with the results of silencing NSD2 in vivo, these findings regarding MCTP-39 treatment suggest that NSD2 may be a target for intervention in advanced prostate cancer." (PMID 30518758, 2018). "Over-expression of NSD2 could promote EMT process and invasive properties of prostate cancer." (PMID 31692936, 2019). "Notably, the activity of NSD2 as a histone methyltransferase has been shown to be coordinately regulated by EZH251, a major component of the histone methyltransferase polycomb repressive complex 2 (PRC2), which is also dysregulated in prostate cancer." (PMID 30518758, 2018). "Therefore, we examined the expression of NSD2 at the mRNA and protein levels in non-metastatic and metastatic contexts in both mouse and human prostate cancer." (PMID 30518758, 2018).
Wolf-Hirschhorn syndrome (29 papers, 2008 to 2024). Wolf-Hirschhorn syndrome (WHS) is a developmental disorder characterized by typical craniofacial features, prenatal and postnatal growth impairment, intellectual disability, severe delayed psychomotor development, seizures, and hypotonia. "Heterozygous loss of NSD2 is responsible for a developmental disease called Wolf-Hirschhorn syndrome (WHS)." (PMID 37150325, 2023). "NSD2 haploinsufficiency is associated with Wolf-Hirschhorn syndrome characterized by heart defects and severe mental and growth retardation." (PMID 36550402, 2022). "Recently, NSD2 gene located within the 165 kb Wolf-Hirschhorn syndrome critical region was identified as the key causal gene responsible for most if not all phenotypes of Wolf-Hirschhorn syndrome." (PMID 33276791, 2020). "Of the same family, NSD2, first identified due to its involvement in chromosomal deletion, causes Wolf-Hirschhorn syndrome (WHS) when mutated." (PMID 31998360, 2019). "WHSC1/NSD2 is a nuclear binding domain associated with the condition Wolf-Hirschhorn syndrome." (PMID 37331566, 2023). "One such histone-modifying enzyme is Wolf-Hirschhorn syndrome candidate 1, WHSC1 (also known as NSD2 and MMSET), mutations in which cause cancer and the human disorder, Wolf-Hirschhorn syndrome (WHS; OMIM 194190)." (PMID 26092122, 2015). "Deletions in NSD2 cause the Wolf-Hirschhorn syndrome (WHS) characterized by delayed growth and intellectual disability while NSD2 overexpression has been linked to cancer (reviewed in Morishita and Di Luccio1)." (PMID 27604143, 2016). "After reviewing more NSD2 mutation cases in pervious literature, we found none of them had facial features that can be recognized as Wolf-Hirschhorn syndrome." (PMID 33276791, 2020).
acute lymphoblastic leukemia (13 papers, 2014 to 2025). Leukemia with an acute onset, characterized by the presence of lymphoblasts in the bone marrow and the peripheral blood. "The NSD2 p.E1099K (EK) mutation is shown to be enriched in patients with relapsed acute lymphoblastic leukemia (ALL), indicating a role in clonal evolution and drug resistance." (PMID 37016431, 2023). "Furthermore, gain-of-function mutations in NSD2 in acute lymphoblastic leukemia (ALL) and several solid tumors enhances methyltransferase activity, thereby driving tumorigenesis." (PMID 41301842, 2025). "FBXO22 targets the degradation of the oncoprotein NSD2 in acute lymphoblastic leukaemia cells." (PMID 39153212, 2024). "LLC0424 potently degraded NSD2 protein with a DC50 value of 20 nM and a Dmax value of 96%in acute lymphoblastic leukemia (ALL) RPMI-8402 cells." (PMID 38687638, 2024). "Thus, Liu’s group designed PROTAC 84 (LLC0424), which degrades NSD2 with nanomolar potency (DC50 = 20 nM, Dmax = 96%) in acute lymphoblastic leukemia (ALL) RPMI-8402 cells." (PMID 40730655, 2025).
breast carcinoma (12 papers, 2018 to 2025). "Our data further show that the inclusion of NSD2 exon 2 is increased in breast cancer and associated with the poor prognosis of patients." (PMID 39667501, 2025). "More importantly, the inclusion of NSD2 exon 2 was associated with poor overall survival of patients with breast cancer of various subtypes." (PMID 39667501, 2025). "Therefore, the data collectively discovered an NSRP1/NSD2/IFN axis implicated in CDK4/6i resistance in ER+ breast cancer cells." (PMID 39667501, 2025). "NSD2 is also closely linked to metastatic progression in human breast cancer." (PMID 41301842, 2025). "More importantly, targeting NSD2 enhanced the vulnerability of breast cancer cells to endocrine therapy." (PMID 39667501, 2025). "NSD2-mediated metabolic reprogramming confers resistance to tamoxifen, an anti-estrogen, and treatment with DZNep, an indirect inhibitor of methyltransferases, induces NSD2 degradation, thus restoring tamoxifen sensitivity in breast cancer." (PMID 41301842, 2025). "Several studies have elucidated the correlation between NSD2 and breast cancer progression and explored its regulatory mechanisms, implying a key role of NSD2 in promoting breast cancer progression." (PMID 40097917, 2025). "For example, NSD2 acts as an essential regulator of estrogen receptor signaling and is a potential therapeutic target for endocrine-resistant breast cancer." (PMID 40097917, 2025). "siRNA-mediated knockdown of NSD2 in our breast cancer cell model significantly abolished the cooperativity between TGF-β and TNF-α for promoting MMP-9 expression, confirming the pivotal role of H3K36m2 chromatin active mark in this synergy." (PMID 39351229, 2024). "Nuclear receptor binding SET domain protein 2 (NSD2), which is upregulated in breast cancer, elevates the expression of G6PD to promote the proliferation of breast cancer cells." (PMID 39516455, 2024). "In breast cancer cells, NSD2 activates WNT/β-catenin signaling to facilitate EMT and invasion." (PMID 41301842, 2025). "Moreover, orthotropic breast cancer model was established by planting the NSD2-knockout 4T1 cells (4T1/NSD2-KO) or control cells into the mammary fat pads of BALB/c nude mice." (PMID 40097917, 2025). "The data suggested that NSD2 exon 2 inclusion might generate oncogenic transcripts in breast cancer cells." (PMID 39667501, 2025). "The protein expression levels of EZH2 and NSD2 were correlated in breast cancer (BC) tissues." (PMID 33665162, 2020). "EZH2 and NSD2 protein expression in breast cancer (BC) and benign lesion tissues." (PMID 33665162, 2020). "Here, we report that NSRP1, a regulator of alternative mRNA splicing is downregulated in CDK4/6i resistant breast cancer cells and contributes to CDK4/6i resistance by mediating alternative splicing of NSD2 mRNA and activation of the IFN signaling pathway." (PMID 39667501, 2025). "To explore the roles and mechanisms of NSD2 in TNBC progression, we first examined NSD2 expression in a panel of 9 commonly studied breast cancer lines that correlated with the receptor status." (PMID 40097917, 2025). "Our data showed that silencing of NSD2 also decreased the expression of the IFN-stimulated genes in ER + breast cancer cells, suggesting NSRP1-regulated AS of NSD2 might contribute to the activity of the IFN pathway." (PMID 39667501, 2025). "However, the regulatory relationship between EZH2 and NSD2 and their prognostic values in breast cancer (BC) have not been fully elucidated." (PMID 33665162, 2020).
leukemia (11 papers, 2015 to 2025). A malignant (clonal) hematologic disorder, involving hematopoietic stem cells and characterized by the presence of primitive or atypical myeloid or lymphoid cells in the bone marrow and the blood. "A frequent NSD2 missense single point mutation (E1099K) was detected in many patients with leukemia." (PMID 37150325, 2023). "We confirmed BRCA1 and NSD2 involved not only in leukemia cell differentiation but also tumorigenesis via regulating c-Myc." (PMID 32826945, 2020). "In addition, RE-IIBP, another short isoform of NSD2 that retains catalytic activity, is upregulate in leukemia patients and contributes to transcriptional repression by promoting H3K27 methylation and histone deacetylation." (PMID 41301842, 2025). "The correlation of NSD2 and H3K36me3 was also observed by ChIP‐seq in K562 human leukemia cells." (PMID 32573059, 2020). "In contrast, the frequently observed T1150A in NSD2 and its T2029A counterpart in NSD1, both observed in leukemia, are hyperactive and introduce up to three methyl groups in H3K36 in biochemical and cellular assays, while wildtype NSD2 and NSD1 only introduce up to two methyl groups." (PMID 37150325, 2023).